PKP2 (plakophilin 2)
Description:
A component of desmosome cell-cell junctions which are required for positive regulation of cellular adhesion. Regulates focal adhesion turnover resulting in changes in focal adhesion size, cell adhesion and cell spreading, potentially via transcriptional modulation of beta-integrins. Required to maintain gingival epithelial barrier function. Important component of the desmosome that is also required for localization of desmosome component proteins such as DSC2, DSG2 and JUP to the desmosome cell-cell junction. Required for the formation of desmosome cell junctions in cardiomyocytes, thereby required for the correct formation of the heart, specifically trabeculation and formation of the atria walls (By similarity). Loss of desmosome cell junctions leads to mis-localization of DSP and DSG2 resulting in disruption of cell-cell adhesion and disordered intermediate filaments (By similarity). Modulates profibrotic gene expression in cardiomyocytes via regulation of DSP expression and subsequent activation of downstream TGFB1 and MAPK14/p38 MAPK signaling (By similarity). Required for cardiac sodium current propagation and electrical synchrony in cardiac myocytes, via ANK3 stabilization and modulation of SCN5A/Nav1.5 localization to cell-cell junctions (By similarity). Required for mitochondrial function, nuclear envelope integrity and positive regulation of SIRT3 transcription via maintaining DES localization at its nuclear envelope and cell tip anchoring points, and thereby preserving regulation of the transcriptional program. Maintenance of nuclear envelope integrity protects against DNA damage and transcriptional dysregulation of genes, especially those involved in the electron transport chain, thereby preserving mitochondrial function and protecting against superoxide radical anion generation. Binds single-stranded DNA (ssDNA). May regulate the localization of GJA1 to gap junctions in intercalated disks of the heart. Involved in the inhibition of viral infection by influenza A viruses (IAV). Acts as a host restriction factor for IAV viral propagation, potentially via disrupting the interaction of IAV polymerase complex proteins.
Synonyms: ARVD9
Tractability: Antibody: its Gene Ontology location is reachable by antibodies, with high confidence. PROTAC: ubiquitination databases record sites on it; its protein half-life has been measured.
Gene: Protein-coding gene on chromosome 12 (32,790,745 to 32,896,798, reverse strand). Ensembl gene ENSG00000057294.
Subcellular location: Nucleus; Cell junction, desmosome; Cell junction; Cytoplasm
Subcellular location (Human Protein Atlas): Cell Junctions; Nucleoplasm
Pathways (Reactome):
Developmental Biology: Formation of the cornified envelope; Keratinization
Gene Ontology:
Molecular function: alpha-catenin binding; cadherin binding; DNA binding; intermediate filament binding; molecular adaptor activity; protein binding; protein kinase C binding; cell adhesive protein binding involved in bundle of His cell-Purkinje myocyte communication; sodium channel regulator activity; transmembrane transporter binding
Biological process: bundle of His cell-Purkinje myocyte adhesion involved in cell communication; cardiac muscle cell action potential involved in contraction; cell-cell signaling; desmosome assembly; intermediate filament bundle assembly; maintenance of animal organ identity; protein localization to plasma membrane; regulation of cell-substrate adhesion; regulation of heart rate by cardiac conduction; regulation of substrate adhesion-dependent cell spreading; regulation of ventricular cardiac muscle cell action potential; ventricular cardiac muscle cell action potential; ventricular cardiac muscle tissue morphogenesis; cell communication by electrical coupling involved in cardiac conduction; cell-cell adhesion; desmosome organization; heart development; maintenance of protein localization at cell tip; positive regulation of sodium ion transport
Cellular component: anchoring junction; cell junction; cell-cell junction; cytoplasm; desmosome; intercalated disc; nucleoplasm; nucleus; plasma membrane; adherens junction; cornified envelope; intermediate filament; membrane; cell tip
Genetic constraint (gnomAD): Loss-of-function variants: 63 observed, 70.32 expected, observed/expected ratio (o/e) 0.9, 90% interval 0.73 to 1.11. The upper end of that interval is the gene's LOEUF score, 1.11, which puts it in group 4 of 6, group 1 being the genes least tolerant of losing a copy. Missense variants: 859 observed, 942.29 expected, observed/expected ratio (o/e) 0.91, 90% interval 0.86 to 0.96. Synonymous variants: 371 observed, 384.21 expected, observed/expected ratio (o/e) 0.97, 90% interval 0.89 to 1.05.
Gene-disease validity (ClinGen):
ClinGen rates the evidence that PKP2 causes each of these diseases.
arrhythmogenic right ventricular cardiomyopathy (autosomal dominant): Definitive.
Brugada syndrome 1 (autosomal dominant): Disputed.
catecholaminergic polymorphic ventricular tachycardia (autosomal dominant): Disputed. Catecholaminergic polymorphic ventricular tachycardia (CPVT) is a severe genetic arrhythmogenic disorder characterized by adrenergically induced ventricular tachycardia (VT) manifesting as syncope and sudden death.
dilated cardiomyopathy (autosomal dominant): Disputed. Cardiomyopathy which is characterized by dilation and contractile dysfunction of the left and right ventricles.
Homologues: Orthologues: chimpanzee PKP2 (99% identical), macaque PKP2 (90% identical), pig PKP2 (88% identical), guinea pig PKP2 (86% identical), dog PKP2 (79% identical), rat Pkp2 (79% identical), mouse Pkp2 (78% identical), rabbit PKP2 (78% identical), tropical clawed frog pkp2 (51% identical), zebrafish pkp2 (35% identical), Caenorhabditis elegans jac-1 (23% identical), Drosophila melanogaster p120ctn (20% identical). Paralogues in human: PKP1 (28% identical), CTNND2 (27% identical), PKP4 (27% identical), PKP3 (24% identical), ARVCF (24% identical), CTNND1 (23% identical).
Diseases named in the same sentence as PKP2 in open-access papers:
PKP2 is named in the same sentence as 94 diseases in open-access papers, as found by Europe PMC text mining. Sharing a sentence is not in itself a finding about the gene and the disease. The quoted sentences say what the papers report.
arrhythmogenic right ventricular cardiomyopathy (53 papers, 2010 to 2026). "The presence of multiple pathogenic variants in desmosomal genes (DSC2, DSG2, DSP, JUP, and PKP2) in patients with arrhythmogenic right ventricular cardiomyopathy (ARVC) has been linked to a severe phenotype." (PMID 37418234, 2023). "A 48-year-old man who was diagnosed with arrhythmogenic right ventricular cardiomyopathy (ARVC) due to a plakophilin 2 gene mutation developed acute both-sided heart failure with rapid atrial fibrillation and was hospitalized." (PMID 35782377, 2022). "The PKP2 gene mutation was reported to associated with arrhythmogenic right ventricular cardiomyopathy (ARVC) and BrS." (PMID 35617207, 2022). "Mutations in PKP2 associate with most cases of gene-positive arrhythmogenic right ventricular cardiomyopathy (ARVC), a pleiotropic disease that can manifest as mainly electrical, structural or both depending on stage progression." (PMID 35663385, 2022). "Most of the reported PKP2 mutations are heterozygous missense and truncating variants, and they are associated with an adult-onset autosomal dominant disorder, namely arrhythmogenic right ventricular dysplasia/cardiomyopathy (ARVD/C)." (PMID 35059364, 2022). "Mutations in the desmosomal protein plakophilin-2 have been associated with arrhythmogenic right ventricular cardiomyopathy." (PMID 33922534, 2021). "In humans, mutation of PKP1 gene caused a skin fragility syndrome characterized by ectodermal dysplasia and skin fragility, mutation of PKP2 gene was closely associated with arrhythmogenic right ventricular cardiomyopathy(ARVC)." (PMID 33088217, 2020). "Mutations or loss of desmosomal components, including Pkp2, are known to compromise desmosome structure and lead to arrhythmogenic right ventricular dysplasia and heart failure." (PMID 22496792, 2012). "On the other hand, arrhythmogenic right ventricular cardiomyopathy, a disease mostly caused by mutations in genes encoding desmosome proteins, including plakophilin-2, plakoglobin, desmoglein-2 and desmoplakin, has been shown to be associated with secondary effects in Cx43 expression." (PMID 33922534, 2021). "Mutations in PKP2 associate with arrhythmogenic right ventricular cardiomyopathy (ARVC)." (PMID 33536940, 2020). "Recently, a homozygous truncating variant in PKP2, a gene previously associated with arrhythmogenic right ventricular cardiomyopathy, was evaluated as causal in two siblings diagnosed with severe HLHS with prominently trabeculated abnormal myocardium and reduced contractility of both ventricles." (PMID 33194928, 2020). "Arrhythmogenic Right Ventricular Cardiomyopathy/Dysplasia (ARVC/D) is mainly caused by heterozygous mutations in genes encoding the main cardiac desmosome components (so-called desmosomal genes hereafter): PKP2, which is the major gene, DSP, JUP, DSG2 and DSC2." (PMID 28767663, 2017). "Moreover, hiPSC-derived cardiomyocyte carrying mutations to plakoglobin and plakophilin-2 recapitulated in vitro arrhythmogenic right-ventricular dysplasia/cardiomyopathy (ARVD/C)." (PMID 28044126, 2016). "For instance, in arrhythmogenic right ventricular cardiomyopathy (ARVC), genetic mutations in desmosomal components such as plakophilin‐2 (PKP2) have been identified as primary pathogenic factors." (PMID 40979216, 2025). "Heterozygous truncating mutations of PKP2 are a common cause of arrhythmogenic right ventricular cardiomyopathy (ARVC) but have also been linked to LVNC in rare cases." (PMID 38370698, 2024). "Loss-of-function variants in PKP2 noted in our patient are known to be pathogenic for autosomal dominant arrhythmogenic right ventricular cardiomyopathy (ARVC)." (PMID 35716983, 2022). "In these experiments, exercise triggered arrhythmogenic right ventricular cardiomyopathy (ARVC) in mice receiving the mutated form of PKP2." (PMID 31316392, 2019).
arrhythmogenic right ventricular cardiomyopathy (continued). "PKP2 gene is located at 12p11.21, and encodes the desmosomal protein plakophilin-2, which is the major genetic cause of arrhythmogenic right ventricular cardiomyopathy (ARVC)." (PMID 30483629, 2017). "Furthermore, arrhythmogenic right ventricular cardiomyopathy (ARVC), usually caused by mutations in PKP2 that encode for the desmosome-related protein plakophilin 2, causes loss of cell-to-cell adhesion in both skin and heart." (PMID 39241028, 2024). "Plakophilin-2 (PKP2) plays a crucial role in cell–cell adhesion and is frequently mutated in inherited cardiac diseases, including arrhythmogenic right ventricular cardiomyopathy (ARVC/ACM) and BrS." (PMID 39596103, 2024). "We divided the AC patients into two groups, DPC carrying DSP gene mutations (nine patients from two different families) and arrhythmogenic right ventricular cardiomyopathy (ARVC) carrying PKP2 gene mutations (six patients from six different families) as per the recent report." (PMID 37450050, 2023). "PKP2 mutations associate with most cases of gene-positive familial arrhythmogenic right ventricular cardiomyopathy (ARVC), a disease characterized by fibrofatty infiltration of right ventricular (RV) predominance, ventricular arrhythmias, and high propensity for sudden death in the young." (PMID 33536940, 2020). "Arrhythmogenic right ventricular cardiomyopathy (ARVC) is a rare but severe cardiac condition frequently associated with mutations of proteins involved in desmosomes (Plakophilin-2, Desmoplakin, Desmoglein-2, and Desmocollin-2), structures involved in the cell–cell interactions." (PMID 33329039, 2020). "Mutations in desmoplakin and plakophilin-2, two genes encoding desmosomal components expressed in the heart, have been implicated in the development of arrhythmogenic right ventricular cardiomyopathy (ARVC)." (PMID 20585603, 2010). "Genetic variants in desmosomal proteins (e.g., PKP2, DSP, DSG2, DSC2) are strongly associated with arrhythmogenic right ventricular cardiomyopathy (ARVC), while mutations in sarcomeric and cytoskeletal genes (e.g., MYH7, LMNA, DES) are linked to hypertrophic and dilated cardiomyopathies." (PMID 41596321, 2026). "Strict spatiotemporal control of [Ca2+]i dynamics is crucial for normal cardiomyocyte function, and recent evidence demonstrated that Cx43 HC opening triggers disturbed [Ca2+]i dynamics in a plakophilin-2–knockout (PKP2-KO) mouse model of arrhythmogenic right ventricular cardiomyopathy (ARVC)." (PMID 36919695, 2023). "Gene PKP2 was found to be responsible for arrhythmogenic right ventricular dysplasia 9 (#609040)." (PMID 35910219, 2022). "We assess the gene-wide and regional association of truncating and missense variants in PKP2 with arrhythmogenic cardiomyopathy (ACM), and arrhythmogenic right ventricular cardiomyopathy (ARVC) specifically." (PMID 34120153, 2021). "One patient was diagnosed with PKP2 (HGNC:9024, NM_001005242.3)-related arrhythmogenic right ventricular cardiomyopathy, VUS was identified in 1 patient and the other patient declined genetic testing." (PMID 39669619, 2024).
cardiomyopathy (44 papers, 2015 to 2025). A disease of the heart muscle or myocardium proper. "Among the proband’s three children, his daughter (III-1) inherited both SCN5A and PKP2 variants, increasing her risk of arrhythmogenic disorders and cardiomyopathies." (PMID 41287789, 2025). "Among HTx recipients, a pathogenic mutation in the RBM20 gene was identified in one patient, while two others carried VUS in TTN and PKP2, which are genes associated with cardiomyopathies." (PMID 40126245, 2025). "Another likely pathogenic gene variant was observed in the PKP2 gene and is in accordance with the observed early cardiomyopathy." (PMID 36816814, 2023). "The cardiomyopathy panel covering 100 known cardiomyopathy genes revealed 2 heterozygous variants of uncertain significance (VUS): PKP2 c.895C>T (p.R299C) and SCN5A c.5872C>T (p.R1958*)." (PMID 37296576, 2023). "The genetic architecture of Plakophilin 2 (PKP2) cardiomyopathy can inform our understanding of its variant pathogenicity and protein function." (PMID 34120153, 2021). "We use human genetics to illuminate detailed gene-wide and region-specific variant–disease association in PKP2 cardiomyopathy." (PMID 34120153, 2021). "A ClinVar search for PKP2 variants based on following diagnoses: “cardiovascular phenotype,” “cardiomyopathy,” “LVNC,” “Paroxysmal familial ventricular fibrillation,” “DCM,” “HCM,” and “ventricular tachycardia,” returns 41 different changes." (PMID 30619891, 2018). "The relation between loss of PKP2 expression and structural cardiomyopathy remains under study, though paracrine activation of pro-fibrotic intracellular signaling cascades is a likely event." (PMID 30568602, 2018). "Our results show that loss of PKP2 in adult myocytes is sufficient to generate an arrhythmogenic cardiomyopathy of RV predominance in mice." (PMID 28740174, 2017). "The data presented here indicate that loss of PKP2 in adult myocytes is sufficient to generate a cardiomyopathy of RV predominance, consistent with other studies suggesting that mechanical stress is a component of the cardiomyopathy." (PMID 28740174, 2017). "Upregulated genes linked to cardiomyopathy included Pkp2, Dst, Dsg2 and Jup; downregulated genes included Pkp1, Dsg1a, Pkp4, Vcl, Gja1 and Ctnna1." (PMID 26935106, 2016). "To investigate whether EPAS1, BNIP3L, and SOD2 induction is a common feature of cardiomyopathy, we also assessed the levels in additional patient hearts with mutations in PKP2 and phospholamban (PLN), associated with ACM and DCM." (PMID 40034852, 2025). "As a different regulation pattern of the TGFβ signaling pathway was observed in samples with mutations in RBM20 and PKP2, this pathway might play a distinct role in different forms of cardiomyopathies." (PMID 33260757, 2020). "The availability of the PKP2cKO murine model has allowed us to examine whether drugs that interfere with pro-fibrotic cascades can blunt the progression of a cardiomyopathy caused by PKP2 deficiency." (PMID 30568602, 2018). "We therefore examined whether an A2AR blocker could change the course of the cardiomyopathy that results from PKP2 deficiency." (PMID 30568602, 2018). "We also speculated that blockade of the A2AR in the heart may slow progression of the cardiomyopathy that results from loss of PKP2 expression." (PMID 30568602, 2018). "Compared to cardiomyopathies caused by variants in DSP, PKP2, FLNC, and LMNA genes, TTN-CMP and sarcomeric gene-related cardiomyopathies tend to exhibit a similar burden of HF events but a generally lower arrhythmogenic profile." (PMID 41329234, 2025). "Levels of cardiomyopathy-related proteins, cadherin-binding proteins, including PKP2, and Ca2+-handling proteins such as RYR2, SERCA2a, and NCX gradually decreased from control through CH to SCD groups." (PMID 41468454, 2025). "We show that a single dose of AAV9:PKP2 gene delivery prevents disease development before the onset of cardiomyopathy and attenuates disease progression after overt cardiomyopathy." (PMID 38499690, 2024).